RNU6-483P (RNA, U6 small nuclear 483, pseudogene)
Gene: Small nuclear RNA gene on chromosome 3 (57,548,838 to 57,548,945, forward strand). Ensembl gene ENSG00000206815.
Homologues: Orthologues: chimpanzee U6 (99% identical), macaque U6 (94% identical), pig U6 (76% identical), guinea pig U6 (74% identical). Paralogues in human: RNU6-1103P (86% identical), RNU6-15P (86% identical), RNU6-345P (86% identical), RNU6-1060P (85% identical), RNU6-116P (85% identical), RNU6-21P (85% identical), RNU6-455P (85% identical), RNU6-477P (85% identical), RNU6-480P (85% identical), RNU6-686P (85% identical), RNU6-1 (84% identical), RNU6-1289P (84% identical), and 1287 more.